ABCG1 (ATP binding cassette subfamily G member 1)
Diseases named in the same sentence as ABCG1 in open-access papers (continued):
Sharing a sentence is not in itself a finding about the gene and the disease.
atherosclerosis (continued). "Moreover, our results also showed that IGFBPL1 inhibits macrophage lipid accumulation by enhancing the activation of IGR-1R/LXRα/ABCG1 pathway, suggesting that targeting IGFBPL1 may be an effective therapy for atherosclerosis." (PMID 38157252, 2023). "ABCA1 and ABCG1 knockout specific to macrophages, and not in hematopoietic stem and multipotential progenitor cells, still leads to monocytosis and neutrophilia and increased atherosclerosis." (PMID 35052806, 2022). "As a vital defense process against the development of atherosclerosis, reverse cholesterol transport contains some steps and the first one is the lipid efflux from cells within the arterial wall, which is modulated by membrane transporters including ABCA1 and ABCG1." (PMID 31379468, 2019). "ABCG1 is not expected to attenuate foam cell formation in early atherosclerosis lesions in humans but could protect from atherosclerosis by preserving vascular endothelium from dietary cholesterol-induced dysfunction." (PMID 30174957, 2018). "However, consistent with what was observed for modulation of whole body Abcg1 expression, those studies led to contrasting results which did not resolve the role of macrophage Abcg1 in atherosclerosis." (PMID 28869506, 2017). "In addition, ABCG1 was reported to protect macrophage from apoptosis induced by oxidized LDL as well as against endothelial dysfunction and activation in mice, which are key features of atherosclerosis." (PMID 28869506, 2017). "Our data showed that mRNA levels of ABCA1 and ABCG1 were increased after the treatment of NLRP3i, suggesting that NLRP3 gene silencing could be a potentially therapeutic mean to increase macrophage cholesterol efflux for the prevention of atherosclerosis." (PMID 24999295, 2014). "Moreover, mRNA levels of ABCA1 and ABCG1 were increased after the treatment of NLRP3i, suggesting that NLRP3 gene silencing could be a potentially therapeutic mean to increase macrophage cholesterol efflux for the prevention of atherosclerosis." (PMID 27239478, 2016). "In mice lacking ApoE, HSP72 accelerates the development of atherosclerosis by inhibiting the production of ABCA1 and ABCG1 in peritoneal macrophages and the aorta through the JNK/Elk-1 pathway." (PMID 37077734, 2023). "While the biochemical events in the RCT pathway have been studied thoroughly, it is still not clear how changes in the functioning of ABCA1, ABCG1, and SCARB1 affect atherosclerosis progression." (PMID 34940525, 2021). "In contrast to what is proposed in mice, human ABCG1 does not promote macrophage cholesterol efflux to HDL and therefore is not expected to attenuate foam cell formation in early atherosclerosis lesions." (PMID 28869506, 2017).
Obesity (39 papers, 2014 to 2025). Accumulation of substantial excess body fat. "Nevertheless, all these obesity-associated pathways were annotated from only 3 genes, namely ABCG1, CPT1A, and SREBF1." (PMID 40702573, 2025). "ABCA1 and ABCG1 promote cholesterol and lipid efflux, mitigating inflammatory effects associated with obesity by maintaining the levels of anti-inflammatory HDL particles." (PMID 40770069, 2025). "Lower expression of ABCG1 in human visceral adipose tissue has been shown to be linked to obesity and metabolic syndrome." (PMID 37507725, 2023). "Multiple of the top DMPs were annotated to genes with relevant functions for diabetes including SREBF1, associated with obesity, type 2 diabetes and insulin sensitivity; ABCG1, involved in cholesterol and phospholipids transport; and HDAC1, of the HDAC family." (PMID 36529747, 2022). "The SREBF1 gene is associated with obesity, type 2 diabetes and insulin sensitivity, and the gene ABCG1 is involved in cholesterol and phospholipids transport." (PMID 36529747, 2022). "Existing data suggests that obesity-related hypertriglyceridemia is associated with CAD risk via ABCG1 gene expression dysregulation." (PMID 34837967, 2021). "Nevertheless, it becomes clear that the epigenetic modulation of ABCG1 is consistently associated with several metabolic disorders, including TG metabolism, diabetes-related traits, T2D risk, obesity and in a lesser degree to CAD." (PMID 28869506, 2017). "Studies in both mice and in humans, demonstrate modulation of ABCG1 expression in association with a large spectrum of metabolic disorders including diabetes, insulin resistance, obesity and CAD." (PMID 28869506, 2017). "Findings from Abcg1-deficient mice suggest that Abcg1 promotes diet-induced obesity through the contribution of adipocyte Abcg1 in adipogenesis and fat mass growth." (PMID 28869506, 2017). "Association of ABCG1 genotype with obesity was replicated in two independent populations composed of either 595 severely obese (35 < BMI < 40 kg/m2) or 216 diabetic obese (30 < BMI < 35 kg/m2) from the diabetes atorvastatin lipid intervention (DALI) subjects." (PMID 28869506, 2017). "Association of the ATP-binding cassette transporter G1 (ABCG1) with obesity was discovered in a screening approach that compared data from the Drosophila melanogaster and mouse genomes." (PMID 24752583, 2014). "In addition, the results of this study showed that FPG, obesity, hypertension, and dyslipidemia were associated with the ABCG1 gene methylation rate and were statistically significant." (PMID 40225014, 2025). "In the whole‐genome association study, one‐third of the differentially methylated genes related to CHD are associated with obesity, among which estrogen receptor 1 ATP binding cassette subfamily G member 1 (ABCG1), and IL6 have been identified as candidate genes for CHD in multiple studies." (PMID 38405061, 2024). "Abcg1, Aldoa, Mrap, Pex13, Aldh6a1, Egln3, G0s2 and Syn2 are significantly increased in adipose or liver tissue of ob/ob mice compared with lean mice, suggesting these genes are associated with obesity, are very rarely reported to be related to adipogenesis." (PMID 34974794, 2022). "Previous studies have demonstrated that methylation of ABCG1 CpG sites cg06500161 and cg27243685 in the blood is positively associated with plasma triglyceride concentration and could be linked to obesity and metabolic syndrome." (PMID 34837967, 2021). "Mutation of ABCG1 protects mice against obesity in a high-cholesterol diet (1%)." (PMID 34884779, 2021). "This study reported for the first time that genetic modulation of ABCG1 was intimately linked to fat mass growth and obesity in humans suggesting that ABCG1 might represent a potential therapeutic target in obesity." (PMID 28869506, 2017). "In addition, LXRα, ABCA1, and ABCG1 expressions were negatively correlated with several obesity-related variables, such as weight, BMI, and hip circumference, reinforcing their association with obesity." (PMID 39062791, 2024).
Obesity (continued). "Moreover, there is now a growing body of evidence suggesting that modulation of ABCG1 expression might contribute to the development of diabetes and obesity, which are major risk factors of CVD." (PMID 28869506, 2017). "The deleterious role of Abcg1 in obesity is supported by genetic modulation of ABCG1 in populations of obese individuals, although analysis of adipose ABCG1 expression following weight loss in both mice and humans appears in contradiction with the proposed model for ABCG1." (PMID 28869506, 2017). "LXRα, ABCA1, and ABCG1 were negatively associated with ALT levels, which is related to lipid metabolism and obesity and reflects hepatocellular injury in patients with NAFLD." (PMID 39062791, 2024). "These include plausible genes such as the cholesterol efflux transporter ABCG1 with a described role in the development of obesity, metabolic disease, and atherosclerotic lesions." (PMID 37672078, 2023). "ABCG1 has been reported to promote LPL-dependent triglyceride storage in adipocytes and to modulate ATM cholesterol content in obesity and weight loss regimes, leading to an alteration in M1 to M2 ratio." (PMID 36557031, 2022). "CpG sites in ABCG1 and PHGDH showed associations with metabolic measures, gene transcription, and metabolic measure ratios and were additionally linked to obesity or previous myocardial infarction, extending previously reported observations." (PMID 33413638, 2021). "ABCA1 and ABCG1 gene expression in subcutaneous and visceral adipose tissue has been shown to be dysregulated in obesity and during metabolic syndrome development." (PMID 34837967, 2021). "DNA methylation levels at the ABCG1 cg27243685 locus in SAT are associated with hypertriglyceridemia and obesity." (PMID 34837967, 2021). "We confirmed that HDAC9 is a transcriptional repressor of the cholesterol efflux ABCG1 gene expression, which is epigenetically modified in obesity and prediabetic states." (PMID 32410704, 2020). "Since the ABCA1, ABCA7 and ABCG1 proteins actmainly in the cholesterol metabolism, and cholesterol dysfunction in the adiposetissue could be related to a lipid imbalance in the whole body, geneticpolymorphisms in the corresponding genes could be involved in obesity-associatedmetabolic complications." (PMID 32745159, 2020). "Both HDAC9 and ABCG1 have been proposed as therapeutic targets for patients with obesity in separate previous studies; however, our data support a mechanistic pathway linking them to metabolic diseases." (PMID 32410704, 2020). "This is of particular interest, as several studies have reported a role of ABCG1 in obesity, insulin resistance and T2D." (PMID 32410704, 2020). "On the contrary, epigenetic modulation of ABCG1 was undoubtedly positively associated with an increased BMI and BMI-related traits which would support a protective role of ABCG1 in obesity." (PMID 28869506, 2017). "ABCG1 (ATP binding cassette G1), a cell-membrane lipid transporter, has an established role in reverse cholesterol transport; its role in obesity is supported in previous animal and human studies." (PMID 28095459, 2017). "In essence, our findings imply that the identified epigenetic loci at CPT1A, SREBF1, and ABCG1 can link obesity to hyperlipidemia (high TG) and elevated postprandial TG response, and then to the risk of CVD." (PMID 27777315, 2016). "Abcg1 is located in a suggestive obesity QTL on proximal Chr 17, and NZO mice carry an insertion of multiple LXR-responsive elements that was associated with higher expression of the gene in white adipose tissue." (PMID 24752583, 2014). "After adjusting for smoking, alcohol consumption, exercise, hypertension, obesity, dyslipidemia, and FPG, there was a statistically significant association between the methylation level of the ABCG1 gene locus and the risk of T2DM (p = 0.015, OR: 1.023; 95% CI: 1.004~1.041)." (PMID 40225014, 2025).
Obesity (continued). "At the same time, the results showed that there were interactions between the ABCG1 gene cg06500161 locus, obesity, dyslipidemia, abdominal obesity, and hypertension (p < 0.05), and there were also interactions between cg06500161 locus and smoking, drinking, and exercise (p < 0.05)." (PMID 40225014, 2025). "Generalized multifactor dimensionality reduction (GMDR) showed that the rs7901695 locus of the TCF7L2 gene and the cg06500161 locus of the ABCG1 gene had interaction with hypertension, dyslipidemia, abdominal obesity, and obesity and also had interaction with drinking, smoking, and exercise." (PMID 40225014, 2025). "In conclusion, this is the first time that it has been described that the expression of LXRα, ABCA1, ABCG1, and Ob-Rb in PBMCs was decreased in patients with MO before and after RYGB and was associated with several variables related to obesity, inflammation, and liver function." (PMID 39062791, 2024). "The combinatorial effects of overweight/obesity and ABCG1 expression were evaluated further." (PMID 38747290, 2024). "Due to its role in lipid regulation, ABCG1 affects lipid levels, obesity and diabetes." (PMID 35655232, 2022). "In this example, 16 DMSs in genes, such as CPT1A, ABCG1, SLC7A11, RNF145, and SREBF1 were reported to be associated with obesity-related phenotypes." (PMID 35047011, 2021). "It is important to mention that adiposity is associated with macrophage infiltration in adipose tissues, and it has been shown that ABCG1 DNA methylation and gene expression could be affected by obesity." (PMID 34837967, 2021). "In addition, it has been reported that ABCG1 modulates M2 macrophage polarization in macrophages under pathological conditions including cancer, obesity and caloric restriction." (PMID 32640667, 2020). "We identified an epigenetic link between adipogenesis and adipose tissue insulin resistance in the context of T2D risk associated with statin use, which has important implications as HDAC9 and ABCG1 are considered potential therapeutic targets for obesity and metabolic diseases." (PMID 32410704, 2020). "Moreover, ABCG1 hosts many kinds of cardio-metabolic phenotypes, including glucose and insulin measurements, type 2 diabetes, and obesity, which are strongly related to cardiovascular diseases." (PMID 31823830, 2019). "Furthermore, they noted that an epigenome-wide association study identified a set of genes, also including ABCG1, related to the pathogenesis of CHD, such as obesity, lipids, and inflammation." (PMID 31823830, 2019). "Unfortunately, the ABCG1 gene was only differentially expressed in the VAT of obesity patients." (PMID 30619480, 2018). "However, genome-wide screens in drosophila and mice led to the identification of Abcg1 as a candidate for TG storage and obesity." (PMID 28869506, 2017). "ABCG1 methylation in SAT could be linked to hypertriglyceridemia and obesity." (PMID 34837967, 2021). "GMDR analysis revealed that the rs7901695 site of the ABCG1 gene and the cg06500161 site of the TCF7L2 gene interacted with hypertension, dyslipidemia, abdominal obesity, and obesity, as well as with drinking, smoking, and exercise." (PMID 40225014, 2025). "After adjusting for smoking, drinking, exercise, hypertension, obesity, dyslipidemia, and FPG, there was no statistical significance between the methylation level of the ABCG1 gene locus and the risk of T2DM (p > 0.05)." (PMID 40225014, 2025). "Their reduced expression could be due to the increased serum LPS levels found in obesity, which repress the expression of LXR and, consequently, of ABCA1/ABCG1." (PMID 39062791, 2024). "ABCG1 codes for an important macrophage cholesterol efflux transporter, necessary for plasma HDL-C formation that has been extensively studied in connection to obesity and metabolic disease." (PMID 37672078, 2023).
Obesity (continued). "In line with this, ABCG1 and, e.g. SREBF1 methylation levels are also known to correlate with T2D, postulating direct or indirect effects on metabolic consequences of obesity." (PMID 37819541, 2023). "The relationship between cg16740586 (located within ABCG1) and diabetes has not yet been reported; however, this is a novel DMP associated with obesity." (PMID 38137029, 2023). "Among the genes affiliated with the 119 significant CpGs, SOCS3 and DOK2 were differentially expressed in the SAT of obesity patients, while seven genes (SOCS3, PRR5L, ABCG1, BRDT, B3GNT7, ZNF710, and RARRES1) were differentially expressed in the VAT of obesity patients." (PMID 30619480, 2018). "Those apparent contrasting observations clearly indicate that the role of adipose ABCG1 is still not yet fully elucidated and that further investigations are required in order to decipher the puzzling role of ABCG1 in obesity." (PMID 28869506, 2017). "However, deletion of Abcg1 in myeloid cells in this study did not improve obesity or glucose intolerance." (PMID 28869506, 2017). "Proprotein convertase subtilisin/kexin type 9 inhibitors improve HDL CEC mediated by ABCG1 and aqueous diffusion in patients with familial hypercholesterolemia, but no data exist specifically in T2DM or obesity to our knowledge." (PMID 36837872, 2023). "For example, obesity has been linked with methylation changes in genes involved in lipid metabolism (ABCG1, SREBF1, and NOD2), which may explain the comorbidities noted in obesity." (PMID 36656735, 2023).